CCDC195 (coiled-coil domain containing 195)
Gene: Protein-coding gene on chromosome 2 (224,703,764 to 224,742,270, reverse strand). Ensembl gene ENSG00000283428.
Homologues: Orthologues: chimpanzee CCDC195 (98% identical), macaque CCDC195 (91% identical), dog CCDC195 (71% identical), pig CCDC195 (69% identical), rabbit CCDC195 (60% identical), mouse Gm45261 (57% identical), rat Ccdc195 (55% identical).